MMP13 (matrix metallopeptidase 13)
Diseases named in the same sentence as MMP13 in open-access papers (continued):
Sharing a sentence is not in itself a finding about the gene and the disease.
tumor (379 papers, 2001 to 2026). "MMPs are involved in inflammation, and increased Mmp13 and Mmp2 expression is associated with increased tumor invasion and cancer progression." (PMID 40437307, 2025). "As such, several studies have already found a significant association between MMP-1, MMP-2, MMP-9, and MMP-13 expression and tumor development, as well as aggressiveness and fast metastatic pattern." (PMID 39063046, 2024). "One mechanism identified to drive such bone loss is the upregulation of matrix metalloprotease 13 (MMP13) at the bone-tumour interface." (PMID 36678864, 2023). "It has also been reported that elevated MMP-13 levels are associated with tumor progression and poorer survival in ESCC patients." (PMID 37609436, 2023). "Overall, MMP-13 overexpression occurs in various cancers, including many common cancer types, and is often associated with tumour aggressiveness, poorer prognosis and reduced patient survival." (PMID 35805035, 2022). "A recent study on esophageal SCC has shown that upregulation of several key molecules (CTLA-4, PD-1, PD-L1, TIM-3, LAG-3) are associated with MMP-13 expression and correlated to tumor progression and invasion." (PMID 35572966, 2022). "Elevated MMP13 expression was not only observed in cancer tissues but also associated with tumor invasion, vascular permeation, and lymph node metastasis." (PMID 30889876, 2019). "Decreased tumor growth in MMP-13(-/-) mice was associated with reduced blood vessel density, and a lack of MMP-13 reduced the vascular density of wound granulation tissue." (PMID 28068383, 2017). "Similar to MMP-2, the collagenases MMP-1 and MMP-13 are expressed in stromal cells, particularly in tumor-associated fibroblasts." (PMID 27271600, 2016). "The current study was designed to establish a translational protocol with regard to a reproducible, specific, and sensitive analysis of the tumor-associated MMP-13 in routinely assessed biopsy specimens from precancerous colorectal lesions." (PMID 27716617, 2016). "To evaluate the role of MMP13 on tumor development, we utilized a splenic injection model of liver metastasis in Wildtype and Mmp13 deficient mice, using either parental or stable Mmp13 knockdown cell lines." (PMID 25880591, 2015). "Transcriptome data from 41 patients showed significant association between MMP13 and spatial tumor shapes." (PMID 26669540, 2015). "Using mice genetically deficient in MMP13 we have shown that loss of stromal MMP13 leads to a significant decrease in the tumor burden in the liver." (PMID 25880591, 2015). "Similar levels of metastatic cell dissemination and early cell survival were observed in wildtype compared to Mmp13 deficient livers, yet the loss of host MMP13 diminished the ability of tumor cells to extravasate." (PMID 25880591, 2015). "The patterns of immunostaining of MMP-7 and MMP-13 correlated well with Bryne's malignancy grading of tumour structure and nuclear polymorphism, thereby indicating that these MMPs can be relevant in gauging the malignancy potential of OSCC." (PMID 26019601, 2014). "Second, we elucidated the underlying molecular basis by identifying MMP13, a gene downstream of the TGFβ signaling that is important in tumor invasion and metastasis, as a target for miR-127 inhibition." (PMID 23762330, 2013). "In agreement, MMP13 expression by intratumoural fibroblasts was significantly associated with shorter relapse-free survival in luminal A tumours." (PMID 24229053, 2013). "KGF also induced downregulation of a set of genes specifically upregulated in SCC cells compared to normal keratinocytes, including genes associated with tumor progression (MMP13, MATN2, CXCL10, and IGFBP3)." (PMID 22427941, 2012). "Focal expression of MMP13 was also detected within tumor-associated stroma or extracellular matrix in 75% of patient samples, and all patient samples showed strong MMP13 immunoreactivity in the vasculature." (PMID 22253746, 2012).
tumor (continued). "MMP-13 is another tumor-derived MMP that is implicated to have cooperative effects with MMP-1 and is related to cancer aggressiveness." (PMID 20946664, 2010). "We found that tumor progression in the MMTV-PyMT model was associated with strong upregulation of the Mmp13 mRNA level as compared to the normal mammary gland." (PMID 18698413, 2008). "To determine if MMP13 plays a role in tumor progression, we crossed MMTV-PyMT mice with Mmp13 deficient mice." (PMID 18698413, 2008). "Moreover, in human GCTb, RUNX2 expression is associated with the upregulation of MMP13, which is the main proteinase expressed by the stromal cell component of the tumor." (PMID 40075982, 2025). "However, due to the lack of relevant studies, conclusions cannot be made, and more studies are needed to reveal the association between MMP13 and viscoelasticity regarding tumour migration." (PMID 40243781, 2025). "Since most of the tumor markers identified so far are not specific to a particular tumor type, we can speculate that EFNA1 combined with MMP13 may also have potential diagnostic value for other tumor types, which needs future evaluation." (PMID 38987376, 2024). "In addition, tumor-associated macrophage (M2Ф) secretes MMP-13 and MMP-3 which are involved in the promotion of metastasis via the IL-17/IL-8 axis." (PMID 36993955, 2023). "MMP-1, MMP-2, MMP-8, MMP-11, and MMP-13 are implicated in the regulation of tumor cell migration." (PMID 36776395, 2022). "Moreover, transcript levels of genes associated with CRC susceptibility loci (e.g., Grem1 and Bmp4) and tumor development and invasion (e.g., Wnt5a, Ereg, Mmp3, Mmp13, Timp1, Saa3, Ptgs2, and Acsl4) were elevated in IL-11+ fibroblasts." (PMID 33863879, 2021). "Similarly, high levels of MMP13 expression are associated with high tumor aggressiveness and poor survival rate." (PMID 29996935, 2018). "Additionally, loss of tumor derived MMP13 through stable knockdown in tumor cell lines lead to decreased migratory and invasive properties in vitro and metastatic burden in vivo." (PMID 25880591, 2015). "The marked decline in the expression of MMP-13 that was associated with advanced stages of tumour invasion could reflect the fact that the BM has already been digested." (PMID 26019601, 2014). "Impaired tumor growth and metastasis have also been shown in MMP-13-deficient mice, which could be attributed to reduced angiogenesis." (PMID 24581230, 2014). "The regulation of these transcription factors may therefore serve as targets in treatment strategies for this destructive tumor and other degenerative diseases of the musculoskeletal system where MMP-13 is the most prominently implicated protease." (PMID 21461405, 2011). "Accordingly, it can be claimed that the presence of MMP-13 might be associated with proliferative activity and tumor aggressiveness." (PMID 18554405, 2008). "Mechanistically, Osx drives expression of matrix-remodeling programs, including MMP13, which supports tumor growth." (PMID 42277024, 2026). "For instance, MMP-13 promotes invasion at the tumor margins, while MMP-7 activates growth factors to drive proliferation." (PMID 40868818, 2025). "The protein expression of TMOD1/MMP13 pathway and tumor invasion-related factors were detected by western blot, illustrating that overexpression of TMOD1 rescued the downregulation of TMOD1 and MMP13, which was caused by high expression of miR-MTCO3P38." (PMID 39744479, 2025). "The ECM’s degradation by MMP13 can release sequestered growth factors, such as fibroblast growth factors (FGFs) and transforming growth factors (TGFs), which aid tumour cell proliferation and are also key to upregulating matrix stiffness." (PMID 40243781, 2025). "MMP13 also exhibits several functions that inhibit tumour progression, such as inhibiting fibrosis and BC lung metastasis." (PMID 40243781, 2025). "Immunohistochemistry further confirmed decreased expression of p-GSK-3β, MMP-9, and MMP-13 in tumor tissues from ArcA-treated mice." (PMID 39948552, 2025).
tumor (continued). "MMP13 not only affects the tumour microenvironment through ECM remodelling, but also indirectly changes the physical properties of tumours by promoting an EMT, reducing intercellular adhesion, and making tumour cells more loosely arranged." (PMID 40243781, 2025). "It has been demonstrated that its overexpression in HT-29 cells promotes invasion angiogenesis and matrix remodeling in models of colon cancer, whereas the silencing of MMP-13 significantly reduces tumor extravasation in the liver in vivo." (PMID 41471689, 2025). "MMP13 directly alters the mechanical properties of the tumour microenvironment by degrading collagen and other matrix components in the ECM." (PMID 40243781, 2025). "Upregulated pro-inflammatory chemokines CXCL6 and CXCL5, along with ECM-degrading enzymes MMP1 and MMP13, create a feedback loop that sustains inflammation and facilitates tumor-supportive immune infiltration." (PMID 40604111, 2025). "Overexpression of MMP-13 correlates with tumor aggressiveness and poor prognosis in breast, colorectal, prostate, bladder, and lung cancers." (PMID 41471689, 2025). "Other proteins present here are involved in matrix remodeling, which can alter tumor invasiveness (MMP13, S100A8, S100A9, and ELN)." (PMID 40699804, 2025). "In contrast, the expression levels of STAT3 downstream target genes—such as VEGFA, IL-6, MMP13, Bcl2, and Twist1—remained comparable across all experimental groups, likely due to tumor excision occurring at a stage when metastasis was already underway." (PMID 40806360, 2025). "Beyond MMP13 expression, CAFs also influence tumour stiffness and development by secreting other factors." (PMID 40243781, 2025). "Similar to MMP7, MMP13 is a key enzyme in cancer progression, promoting tumor cell migration, metastasis, and angiogenesis by degrading the extracellular matrix and activating epithelial-mesenchymal transition (EMT), thereby enhancing tumor invasiveness." (PMID 40168262, 2025). "bsPD-L1 expression in GC was associated with IFN-γ levels and intra-tumoral T cell infiltration, whereas MMP13 levels were associated with loss of ECM integrity, allowing tumor cells to access blood vessels." (PMID 38774209, 2024). "Mmp1a, Mmp3, and Mmp13, which engage in metastasis through facilitating invasion of tumor cells, were downregulated in Setd7 KO and CPH groups compared to Setd7 WT group." (PMID 39522095, 2024). "In Papadopoulou's study, the increase in MMP1 and MMP13 expression followed by the decreased expression levels of CD44 was found to promote tumor growth." (PMID 38783892, 2024). "MMP-10 can also upregulate the expression of MMP-7, MMP-9, and MMP-13, which are critical for tumour progression." (PMID 38911387, 2024). "On the contrary, a statistically significantly higher number of cells producing ASPH (p < 0.0001), HIF1A (p < 0.0001), GLUT1 (p < 0.0001), and MMP13 (p < 0.05) proteins were detected in the HPV-positive tumor group than in the HPV-negative sample group." (PMID 38858774, 2024). "MMP13 plays a role in the degradation of basement membrane and extracellular components, destroys the histological barrier of tumor invasion, and promotes tumor invasion and migration." (PMID 38987376, 2024). "For example, MMP13 (Matrix Metalloproteinase 13) secreted by fibroblasts promotes tumor angiogenesis, while MMP2 (Matrix Metalloproteinase 2) and MMP9 (Matrix Metalloproteinase 9) degrade ECM (Extracellular Matrix) components to promote metastasis." (PMID 38782818, 2024). "In GC, MMP13 was reported to be up-regulated in tumor tissues and its positive expression was related to poorer survival." (PMID 38987376, 2024). "The collagenases we found to be secreted in a PKD-regulated manner, MMP-1 and MMP-13, are released by tumor cells to degrade both the basement membrane and the ECM to allow cancer cell invasion and metastasis to distant organs." (PMID 38323010, 2024).
tumor (continued). "Amongst the upregulated matrisome‐associated genes in low HDM uLMS tumours, we found the ECM‐degrading MMP13 and ADAMTS20, further suggesting increased ECM proteolysis in uLMS tumours." (PMID 37078535, 2024). "MMP13 expression had a significant impact on the architecture of connective tissue and the migration of both T cells and tumor cells in the TME." (PMID 38774209, 2024). "RNA sequencing analysis revealed that matrix metalloproteinase 13 (MMP13) and WNT7B genes are upregulated in UPS, which are linked to enhanced cell migration and tumor aggressiveness." (PMID 39474109, 2024). "This is consistent with previous reports which have identified a role for MMP13 in the progression of a number of tumor types, including head and neck and cSCC." (PMID 38982038, 2024). "The obtained data showed that the baseline Mmp13 expression in the Myd88KO group was higher compared to Myd88KO tumor samples (p = 0.022)." (PMID 39000291, 2024). "The matrix metalloproteinase 13 (Mmp13)gene, responsible for the breakage of the extracellular matrix and tumor cell invasion, is also three times downregulated in the Myd88KO tumor group compared to WT." (PMID 39000291, 2024). "MMP-10 can also upregulate the expression of MMP-7, MMP-9, and MMP-13, which are critical for tumor progression." (PMID 39247608, 2024). "MMPs can be divided six subfamilies, of which MMP1 and MMP13 are collagenases and MMP3 and MMP10 are stromelysins, which have long been associated with tumor invasion, metastasis and angiogenesis." (PMID 36824434, 2023). "Heightened MMP-13 expression, especially in cancer, facilitates tumour invasion into nearby tissues." (PMID 38067138, 2023). "The luciferase activity of these cells in the Runx2-expressed tumor cells gradually decreased with the increased expression of E-cadherin, indicating that E-cadherin inhibited MMP13 transactivation in a dose-dependent manner in the Runx2-expressed tumor cells." (PMID 37150786, 2023). "Following carboplatin treatment, CAFs increased their expression of numerous MMP genes (Mmp2, Mmp3, Mmp13, Mmp14, Mmp27); proteases involved in the degradation of the tumor-supporting matrix." (PMID 37660083, 2023). "IL-11 upregulates MMP-13 expression by activating PI3K, Akt, and AP-1 signaling pathways that subsequently enhances MMP-13-induced tumor metastasis." (PMID 37199584, 2023). "Matrix metalloproteinase 13 (MMP-13) promotes tumor invasion and metastasis by mediating the degradation of the epithelial basement membrane and extracellular matrix." (PMID 37936981, 2023). "Meanwhile, both Se-PC PDT and PC PDT treatment inhibited tumor initiation and metastasis by downregulating the expression levels of Vegfa, Mmp13 and Serpinel via the HIF-1 pathway and IL-1b and Nfkbia via the NF-κB and TGF-β signaling pathways." (PMID 37994159, 2023). "MMP-9 and MMP-13 are important for the degradation of the basal layer membrane and the extracellular matrix, thus favoring tumor infiltration and metastases." (PMID 36831458, 2023). "Our data showed that both Se-PC PDT and PC PDT treatment markedly downregulated the gene expressions of Vegfa, Ppbp, Mmp13 and Serpine1 to inhibit tumor proliferation and metastasis." (PMID 37994159, 2023). "We also noticed 18 Hox genes, Mmp13, Tbx, Pdk4, Bmp and other proven tumor-related genes in the list." (PMID 37696812, 2023). "MMP13 KO mice implanted with mammy tumour cells show increased lung metastasis as a result of increased collagen synthesis and altered collagen structure and organization." (PMID 36190948, 2022). "Two studies have reported that tumor cells can release TEX enriched in matrix metalloproteinase-13 (MMP-13) and miR-21, thus enhancing metastasis occurring via epithelial-mesenchymal transition (EMT) under hypoxic conditions." (PMID 35163380, 2022). "cSCC patients' tumor tissues exhibited a notably higher level of MMP-13 compared to control tissues." (PMID 35572966, 2022).
tumor (continued). "CD40 agonistic mAbs can induce TAMs to secrete high levels of matrix metalloproteinase 13 (MMP13), an enzyme that supports tumor control by degrading fibrotic tissue." (PMID 36679900, 2022). "Among them, MMP13 was most remarkably downregulated, belongs to the matrix metalloproteinase family, and contributes to tumor metastasis." (PMID 35690612, 2022). "Collagenase MMP-13 expression was low to undetectable in normal skin samples, whilst in 9/9 tumor samples an overexpression was evident and confirmed by densitometric analysis." (PMID 36713871, 2022). "MMP-13 also participates in the process of tumour cell infiltration into the blood or lymphatic vessels during metastasis." (PMID 35805035, 2022). "The inhibition of MMP-13 expression by hammerhead ribozyme suppresses squamous cell carcinoma tumour growth and reduces the number of proliferating cells within the tumours." (PMID 35805035, 2022). "Western blotting was used to assess the levels of ENO1, c-Myc, β-catenin, MMP-9, PGAM1, and MMP-13 in SKCM-derived cell lines or tumor tissues from patients with SKCM." (PMID 35925486, 2022). "Mechanistic studies have shown that SLIT2-activated macrophages have high phagocytic capacity, are polarized into an anti-tumor M1 phenotype, and inhibit tumor fibrosis by activating MMP13 secreted by macrophages." (PMID 36591235, 2022). "Overall, the expression and presence of MMP-13 in cancer and stromal cells is actively involved in promoting angiogenesis in tumour cell metastatic spreading." (PMID 35805035, 2022). "MMP13 plays a critical role in the metastasis of tumor cells through the degradation of extracellular matrix proteins." (PMID 37304008, 2022). "Overlap of upregulated genes in the tumor tissue with downregulated genes in the cell line treated with pazopanib identified three genes involved in cancer invasion and metastasis (MMP13, ST6GAL2, and ENPP1)." (PMID 35365682, 2022). "Overall, MMP-13 makes important contributions to tumour cell invasion at primary tumour sites, as well as the establishment of tumour cells at remote organs in metastasis through the degradation and remodelling of ECM and the activation of other MMPs." (PMID 35805035, 2022). "The role of Mmp13 in regulating osteoclast differentiation and resorption has been studied in various tumor models." (PMID 35281094, 2022). "Immune blot results showed that MMP2, MMP9, and MMP13 (migration marker proteins) expression decreased in tumor tissues of anti‐Chi3L1 antibody‐treated mice." (PMID 34861103, 2022). "The presence of CAFs within the tumor, quantitatively depicted as FAP positivity, was strongly linked to the expression of MMP13, AKT1, TGFB3 and TGFBR2, among other factors." (PMID 35311102, 2022). "MMP-13 can also be activated by MMP-3 and the major isoenzyme of human tumour-associated trypsinogen, trypsin-2." (PMID 35805035, 2022). "Tumour cells also produce parathyroid hormone-related protein (PTHrP) to induce MMP-13 expression through the activation of protein kinase C (PKC)-ERK1/2 signalling." (PMID 35805035, 2022). "Increased expression of MMP-13 in tumour or stromal cells alters the collagen concentration in ECM and creates a more favourable environment for tumour growth." (PMID 35805035, 2022). "The production of MMP-13 is tightly controlled in physiological conditions but is increased in various cancers and plays multiple roles in tumour progression and metastasis." (PMID 35805035, 2022). "MMP13 (matrix metallopeptidase 13) had been shown to be expressed in the invading front of the tumour and in stromal fibroblasts and its expression was significantly higher in large (>4 cm) locally invasive tumours." (PMID 35326543, 2022). "Significant relationships between tumor podoplanin and tumor MMP-13 were consistent with previous findings linking MMP-13 overexpression to advanced staging and lymph node metastases." (PMID 36505148, 2022).